INS (insulin)
Diseases named in the same sentence as INS in open-access papers (continued):
Sharing a sentence is not in itself a finding about the gene and the disease.
Obesity (continued). "Although insulin lowers postprandial blood glucose, the chronic hyperinsulinemia that can be detected in metabolic disorders such as obesity and PCOS does not induce hypoglycemia." (PMID 40013621, 2025). "This comes as no surprise as the rates of pediatric overweight, obesity and adiposity are increasing in the general population as well as among CwD where the anabolic effects of insulin play an additional role." (PMID 40846804, 2025). "Adipose tissue, especially in the context of obesity, acts as an immunologically active organ, releasing pro-inflammatory cytokines such as TNF-α, IL-6, and IL-1β, which impair insulin signaling, promote endothelial dysfunction, and contribute to vascular inflammation." (PMID 40870891, 2025). "Conversely, deletion of adipocyte Fam20c after established obesity and hyperglycemia improved glucose tolerance, augmented insulin sensitivity, and reduced visceral adiposity, without altering body weight." (PMID 41148235, 2025). "Elevated free fatty acids (FFAs), common in obesity, accumulate in non-adipose tissues such as the liver and muscle, leading to lipid-induced insulin resistance of the tissues." (PMID 39857741, 2025). "As a result, treatments developed for obesity or T2DM may offer therapeutic potential for AD, particularly those targeting insulin and leptin pathways." (PMID 40808704, 2025). "A key consideration is that, regardless of body weight, obesity-related morbidity and mortality depend on the distribution of adipose tissue, particularly in tissues that rely on insulin and within hepatocytes." (PMID 40219026, 2025). "Although key lipid metabolism and inflammation-related genes were assessed, other important pathways and factors involved in obesity, such as gut microbiota composition, insulin signaling, and adipokine levels, were not investigated in this study." (PMID 39974837, 2025). "However, upon HFD feeding, Mlkl−/− mice exhibited lower serum insulin, ALT, and cholesterol levels, compared with HFD-fed WT controls, supporting the idea that MLKL drives obesity-induced metabolic dysfunction." (PMID 39532538, 2025). "In contrast to obese and insulin-resistant children and adolescents, persons with obesity and insulin sensitivity had no substantial variations in hormonal responses when compared to normal-weight controls." (PMID 40649920, 2025). "Ongoing efforts to develop IDE activators and insulin-sensitizing agents aim to alleviate amyloid burden and delay cognitive decline, positioning IDE-centered interventions as a critical component of future AD treatment in the obesity context." (PMID 41155642, 2025). "Compared with insulin initiators, SGLT2i initiators (n = 1009) had a higher prevalence of cardiovascular comorbidities and proteinuria, while GLP1RA initiators (n = 2149) had a higher prevalence of obesity." (PMID 39860655, 2025). "Pro-inflammatory Mediators Obesity-induced inflammation in AT involves macrophage infiltration and stress pathway activation, with NF-κB driving production of cytokines (TNF-α, IL-6, IL-1β) that disrupt insulin signaling." (PMID 40630101, 2025). "Unlike PCOS in lean patients, in patients with obesity, IR is usually a result of adiposity and decreased tissue sensitivity to insulin." (PMID 40869469, 2025). "Interestingly, while exendin-4 (a GLP-1 agonist) elicited preserved insulin release under a chow diet despite macrophage Gq activation, the same response was blunted in HFD-fed mice, indicating that obesity sensitizes β-cells to this inhibitory pathway." (PMID 41278909, 2025). "The current study investigated the effects of a lack of maternal Sst exposure on obesity development, glucose tolerance and peripheral insulin sensitivity in offspring challenged with or without a HFD." (PMID 40066865, 2025).
Obesity (continued). "Incretin-based anti-obesity therapies (e.g., GLP-1 receptor agonists such as semaglutide; dual GIP/GLP-1 agonists such as tirzepatide) improve adiposity, insulin resistance, and inflammatory profiles, providing a biologically plausible pathway for endometrial risk modification." (PMID 41301707, 2025). "Finally, long-term CR has a protective role with respect to overweight/obesity, T2D, and inflammation and reduces levels of total cholesterol, LDL cholesterol, TG, fasting blood glucose, and plasma insulin." (PMID 40136716, 2025). "A study surveying MSTN serum concentration in human adults found a positive correlation between obesity and increased MSTN, a positive association with insulin resistance, and a negative correlation with insulin sensitivity." (PMID 39340593, 2025). "In people living with obesity, a reduction in this factor may facilitate increased insulin secretion by indirectly affecting VAMP2, a key protein in insulin exocytosis." (PMID 40149500, 2025). "In addition to improving glucose tolerance and reducing insulin resistance in the homeostatic model, Z. lotus fruit powder improved the levels of circulating glucose and insulin in HFD-induced obesity in C57BL/6j mice." (PMID 40035065, 2025). "The overexpression resulted in a significant impairment in insulin tolerance and increased plasma cholesterol following HFD, highlighting a critical role of ETB receptor in adipocytes to promote metabolic dysfunction in HFD‐induced obesity." (PMID 40969148, 2025). "For instance, GPR43 binds to short-chain fatty acids to enhance insulin secretion in cells; GPR75 can recognize 20-HETE and regulates obesity; and GPR40 and GPR120 can improve glycemic control, increase insulin sensitivity, and reduce inflammation via incretin release." (PMID 40892510, 2025). "Key clinical risk factors include maternal age, pre-pregnancy obesity, excessive weight gain before and during pregnancy, and gestational diabetes (GDM) that has not progressed to insulin therapy." (PMID 39940917, 2025). "Previous studies have shown that BGU is increased upon insulin stimulation in people with obesity and IR but not in normal weight people." (PMID 40926735, 2025). "HDL-C showed positive correlations with QUICKI, BUN, and serum adiponectin, while negative correlations with the number of MetS criteria, obesity parameters (BMI, %fat, and fat mass), IR parameters (plasma insulin and HOMA-IR), plasma TG, and serum leptin." (PMID 41162612, 2025). "Cafeteria diet induced significant obesity (mean weight 426.76 g vs. 263.09 g controls, p < 0.001) and increased leptin levels without altering insulin, IGF-1, or inflammatory markers." (PMID 40806434, 2025). "Furthermore, the authors demonstrate the involvement of these microRNAs in key metabolic pathways, including FoxO, insulin, Ras, and AMPK-mediated signaling cascades, highlighting their regulatory role in the pathogenesis of obesity." (PMID 40869388, 2025). "Another study observed that even in women with mild GDM, insulin therapy during pregnancy did not reduce the likelihood of developing obesity or metabolic syndrome 5 to 10 years post-delivery." (PMID 40076938, 2025). "These greater changes may be partly explained by enhanced adipokine regulation and improved lipid metabolism, which collectively contribute to better insulin sensitivity and HDL-C elevation in individuals with obesity." (PMID 41228493, 2025). "The GM contributes to obesity pathogenesis through multiple mechanisms, including SCFA-mediated regulation of energy homeostasis and insulin sensitivity, LPS-induced chronic inflammation, modulation of host metabolic and appetite-regulating genes, and alterations in BA signaling via FXR." (PMID 41007736, 2025). "According to a systematic review, aerobic exercise interventions improve fasting insulin levels, insulin resistance, blood lipid levels, LDL, leptin and cortisol levels, and blood visfatin levels in children and adolescents with overweight and obesity." (PMID 40868462, 2025).
Obesity (continued). "Some theories to explain the reason include cardio‐protective effects of increased body mass due to increased nutritional reserves, and improved insulin sensitivity for mitigating negative impacts of obesity have been proposed." (PMID 40575865, 2025). "Type 2 diabetes in Japan and East Asian countries is often characterized by non-obesity and impaired insulin secretion, contrasting with the obesity-driven insulin resistance more commonly seen in Caucasian populations." (PMID 40607140, 2025). "For example, in obesity, specific inflammatory factors such as interferon-γ, tumor necrosis factor (TNF), leptin, insulin, and palmitate activate the mTORC1 pathway, enhancing macrophage glycolysis activity, thereby increasing PD-1 surface expression and suppressing T cell activity." (PMID 40055311, 2025). "In addition to its anti-adipogenic effects, ASA also reduces the obesity-induced expression of inflammatory cytokines (IL-6, TNFα, and MCP-1) and adhesion molecules (ICAM-I and VCAM-I) while enhancing insulin sensitivity in high-fat diet-induced obese mice." (PMID 39859567, 2025). "The serum insulin concentrations and HOMA-IR at different time points of OGTT, serum TG, TC and LDL-C concentrations in women of vitamin D group (obesity) were significantly lower compared with control group (obesity) (P < 0.05)." (PMID 39014475, 2024). "This is an anticipated effect when surplus carbohydrate intake occurs and supports that obesity had not occurred to such a great extent that insulin resistance had occurred." (PMID 38166559, 2024). "Additionally, it can enhance lipid metabolism and insulin sensitivity through the SREBP-1c/PPARα signaling pathway, thereby preventing dietary obesity and related metabolic disorders." (PMID 38731261, 2024). "However, 5-HIAA derived from gut microbiota can improve glucose intolerance and obesity in HFD-fed mice, while preserving hepatic insulin sensitivity via directly activating AHR, which stimulates TSC2 transcription and thus inhibits mTORC1 signaling." (PMID 39426289, 2024). "Mechanisms that may contribute to obesity include the role of FMO 3 (TMAO producing enzyme) in obesity regulation and adipose tissue formation, as well as increased hepatic insulin resistance and consequent obesity through increased TMAO concentrations." (PMID 38699314, 2024). "Male offspring exposed to GIH in utero demonstrate negative health outcomes such as obesity, altered blood insulin and lipid profiles, and epigenetic changes in white adipose tissue." (PMID 39036336, 2024). "Obesity plays an inevitable role in the increased prevalence of type 2 DM, a chronic condition where the body fails to produce sufficient insulin or cannot efficiently utilize insulin resulting in elevated blood glucose levels as its primary manifestation." (PMID 38339160, 2024). "This dietary intervention proved to be safe for individuals with T2D who were not on sulfonylureas or insulin, and it holds promise as a complementary approach in T2D management but also as an intervention for overweight/obesity individuals without T2D." (PMID 39273678, 2024). "Recent research also found that inactive women with obesity who performed high-intensity training combined with early TRE showed greater improvement in total cholesterol, triglyceride, insulin, HOMA-IR, and glucose compared to a control group that only followed TRE." (PMID 39614235, 2024). "Supportively, acute (6 h) exposure of L6 myotubes to visceral, but not SAT secretome from individuals with extreme obesity impaired insulin-stimulated glucose uptake." (PMID 37801203, 2024). "In addition to insulin, the transport of the hormone leptin across the BBB is also altered in obesity." (PMID 38678254, 2024). "Because the indocyanine green (ICG) infusion was not started properly during the low-dose insulin infusion for 1 man with obesity, we imputed leg and splanchnic plasma flow for that interval using data from the preceding and following intervals." (PMID 38602778, 2024).
Obesity (continued). "First, we showed that under insulin clamp conditions, renal cortex GU rates were lower in patients with obesity compared with nonobese controls, confirming our previous study." (PMID 37955868, 2024). "In a separate study, an ABA-enriched extract at 0.125 μg/kg body weight improved glucose tolerance, insulin sensitivity, and fasting blood glucose in diet-induced obesity (DIO) and db/db mouse models, without increasing insulin levels." (PMID 39796447, 2024). "In obesity, increased blood–brain barrier (BBB) permeability may allow more insulin to enter the brain, contributing to neuronal IR, possibly through receptor desensitization, a process thought to worsen with aging." (PMID 39684879, 2024). "In addition, serum levels of miR-15b and miR-146b were increased in children with obesity and adults with T2D, and overexpression of miR-15b and miR-146b in pancreatic β-cell line MIN6 cells decreased insulin secretion." (PMID 38642584, 2024). "Conditions such as obesity or PCOS itself are associated with hyperinsulinemia and IR when, despite normal pancreatic function, the insulin produced fails to carry out its action and accumulates in the plasma." (PMID 38172476, 2024). "In the total cohort, increased ST was inversely associated with insulin and HOMA-IR, but increased ST was positively associated with hyperinsulinemia in participants with overweight and obesity independent of LPA and MVPA." (PMID 38441224, 2024). "Moreover, elevated miR-26a levels have been demonstrated to reduce glucose-stimulated insulin secretion (GSIS), which helps to mitigate hyperinsulinemia—a key factor in both T2DM and obesity." (PMID 39684879, 2024). "Fructosamine concentrations were also not different between overweight and lean dogs, again contrasting with previous research where greater fructosamine concentrations were seen in insulin-resistant, but not insulin-sensitive, dogs with obesity." (PMID 39296580, 2024). "There was a trend for interrupting sitting with light walking to attenuate postprandial glucose area under the curve (by 13% for iAUC) in South Asians with overweight/obesity, whereas no such trend was apparent for postprandial insulin." (PMID 37950762, 2024). "In another independent study, circulating total ceramides were inversely correlated with whole-body insulin sensitivity in subjects with obesity and insulin resistance (with and without MASLD/MASH) who were eligible for bariatric surgery." (PMID 38962680, 2024). "By focusing on non-scale victories such as improved insulin sensitivity, lipid profiles, and mental health, dietitians play a crucial role in driving long-term success in obesity management." (PMID 39519418, 2024). "Therefore, because of its significant role in controlling energy metabolism and involvement in insulin signaling, it remains important to establish how HFD affects skeletal muscle function in preclinical models of obesity." (PMID 38044359, 2024). "Both circulating insulin and IGF-1 are increased in obesity." (PMID 39201522, 2024). "Overall, our study further strengthens the notion that independent of genetics, obesity increases pancreatic fat content and insulin secretion." (PMID 39334836, 2024). "The mice do not exhibit overweight or obesity characteristics, and there is no IR with low serum insulin, low fasting blood glucose, and low leptin." (PMID 39840105, 2024). "Our metabolic screening also showed that U90926 deficiency does not impact other major plasma biomarkers of obesity, such as fibroblast growth factor 21 (FGF21), leptin, and insulin." (PMID 38171546, 2024). "Nevertheless, there is sufficient evidence showing that children with obesity do not recover baseline insulin sensitivity at the end of puberty." (PMID 38289144, 2024).
Obesity (continued). "Notwithstanding the fact that despite the BMI and HOMA-IR tended to be higher in women of the PCOS group compared to the control group these were well balanced between groups and the average did not fall in the obesity nor insulin resistant range." (PMID 39011395, 2024). "While groups of a lean/healthy weight demonstrated a significant difference in response to insulin compared to the control substance (p = 0.04), the groups affected by overweight/obesity did not (p = 0.7)." (PMID 39595054, 2024). "It does not aim to exhaustively cover all molecular alterations linked to the pathogenesis of IR, or the advancements in understanding insulin signaling components downstream of the INSR, which may be altered in obesity." (PMID 39337290, 2024). "Further elegant studies revealed that mice lacking TNF function exhibited improved insulin sensitivity and had lower levels of circulating free fatty acids in diet-induced obesity models." (PMID 38672492, 2024). "The chronic consumption of a HFD in women with obesity and T2DM may enhance IR, potentially impacting reproductive function through elevated serum insulin levels constantly stimulating insulin pathways in the ovaries and pituitary." (PMID 39006367, 2024). "Subjects with high neutrophilic CLSs exhibited significantly higher parameters for obesity (BMI and waist circumference), hepatocellular injury (ALT and AST), and dysfunctional glucose metabolism (fasting blood glucose, blood insulin, HOMA-IR, and blood C-peptide) relative to those with low CLSs." (PMID 38812532, 2024). "The results of our study show that pregnancy hyperglycaemia driven by impaired insulin secretion in absence of obesity has a clear contribution to the development of postpartum MASLD." (PMID 38918525, 2024). "Instead, a 9-week-long supplementation with a 10% fructose solution induced tissue-specific metabolic disturbances, for instance, adipogenesis, inflammation, and insulin resistance in the visceral adipose tissue without the development of obesity." (PMID 39519293, 2024). "This leads to oversupply of the energy substrates to insulin-sensitive cells in the absence of obesity, leading to mitochondrial overload and excessive ATP production." (PMID 39873003, 2024). "Obesity results in the overactivation of the Sympathetic Nervous System (SNS) due to adipokine secretion, stimulation of the Renin–Angiotensin–Aldosterone System (RAAS), insulin resistance, baroreceptor dysfunction, and obstructive sleep apnea." (PMID 38297370, 2024). "While both maternal pre-pregnancy obesity and excessive GWG appear to correlate with elevated blood pressure, unfavorable lipid profiles, and insulin resistance in childhood, there is some indication that these connections are largely influenced by childhood BMI." (PMID 39331227, 2024). "Moreover, studies suggest a potential role for antibiotics, particularly vancomycin, in treating dysbiosis related to obesity by reducing TNF-α levels in mice and increasing insulin sensitivity in humans." (PMID 39596385, 2024). "These miRNAs showed a strong correlation with various obesity markers, including body mass index (BMI), waist/hip ratio (WHtR), adipokines, adiponectin, leptin and fasting blood sugar levels (FBS), insulin, HOMA-IR, triglycerides (TG), HDL-C, C-peptide and LDL-cholesterol." (PMID 38541185, 2024). "Moreover, studies in humans and mice have demonstrated a positive correlation between the level of activated BAT and insulin sensitivity, hinting at the potential application of strategies to augment BAT quantity or activity in obesity and diabetes treatment." (PMID 38721091, 2024). "Splanchnic palmitate delivery was greater in participants with obesity than participants without obesity only during the low-dose insulin clamp (P = 0.003)." (PMID 38602778, 2024).